SETD2 (SET domain containing 2, histone lysine methyltransferase)
Diseases named in the same sentence as SETD2 in open-access papers (continued):
Sharing a sentence is not in itself a finding about the gene and the disease.
mastocytosis (2 papers, 2019 to 2025). A clonal myeloproliferative neoplasm characterized by the proliferation and accumulation of neoplastic mast cells in one or multiple organs or organ systems. "Genetic alterations in the SETD2 gene may contribute to altered methylation patterns that support mast cell proliferation and survival, potentially influencing mastocytosis development." (PMID 41031827, 2025). "The results align with our previous findings, which determined TET2, DNMT3A, SETD2 and BRD4 genes as promising candidates for further analysis, warranting future study in a larger cohort of mastocytosis patients." (PMID 41031827, 2025).
myeloid malignancies (2 papers, 2017 to 2019). "Mutations of SET domain‐containing 2 (SETD2), a methyltransferase that catalyses the trimethylation of histone 3 on lysine 36 (H3K36me3), were found in various myeloid malignancies." (PMID 31054182, 2019).
osteomyelitis (2 papers, 2024 to 2025). An acute or chronic inflammation of the bone and its structures due to infection with pyogenic bacteria. "Utilizing a murine osteomyelitis model induced by Staphylococcus aureus, we conducted a comprehensive investigation of the in vivo functions and mechanisms of HIF-1α and SETD2 in the development and progression of osteomyelitis." (PMID 38830934, 2024). "In summary, our study has uncovered a previously unrecognized role of SETD2 in facilitating osteomyelitis recovery and augmenting osteogenic differentiation of hBMSCs within a co-culture system." (PMID 38830934, 2024). "To examine the role of SETD2 in macrophage function during osteomyelitis, we analyzed the expression levels of SETD2 in TPH-1 cells upon stimulation with SPA." (PMID 38830934, 2024). "Despite its importance, the role of SETD2 in osteomyelitis remains enigmatic." (PMID 38830934, 2024). "This research has uncovered a previously unknown role of SETD2 in macrophages during osteomyelitis, revealing its significance in the pathogenesis of this condition." (PMID 38830934, 2024). "Hence, the modulation of M1-like macrophages via SETD2 could offer a promising novel therapeutic strategy for bone regeneration in acute suppurative osteomyelitis." (PMID 38830934, 2024). "Based on these findings, we hypothesized that SETD2 might regulate the expression of HIF-1α, thereby modulating macrophage glycolysis in osteomyelitis." (PMID 38830934, 2024). "Furthermore, this study reports for the first time that SETD2 suppresses M1 macrophage polarization and glycolysis by regulating HIF-1α via catalysis of H3K36me3 in the context of osteomyelitis." (PMID 38830934, 2024).
pancreatic ductal adenocarcinoma (2 papers, 2020 to 2021). An infiltrating adenocarcinoma that arises from the epithelial cells of the pancreas. "Approximately 3% (n = 775) of pancreatic ductal adenocarcinoma (PDAC) patients carry SETD2 mutations, and nearly all cases with SETD2 mutation have aberrant KRAS, the most common mutation site in PDAC." (PMID 34715919, 2021). "Sun group reported that SETD2 loss did not affect Wnt/β-catenin signaling in pancreatic ductal adenocarcinoma cells in the context of KrasG12D9." (PMID 32849799, 2020).
pleural mesothelioma (2 papers, 2016 to 2022). A neoplasm that arises from the mesothelial cells of the pleura.
primary immunodeficiency (2 papers, 2019 to 2025). "Lastly, SETD2 is frequently mutated in patients with primary immunodeficiency." (PMID 31350389, 2019). "Moreover, two missense SETD2 mutations that impair the enzymatic activity of SETD2 are identified in primary immunodeficiency disorder patients, providing support for the clinical relevance of SETD2 mutations in the development of human primary immunodeficiency." (PMID 40746737, 2025).
sarcoma (2 papers, 2019 to 2023). A usually aggressive malignant neoplasm of the soft tissue or bone. "Additionally, novel features of canine OS merit further exploration including the potential roles of SETD2 and DMD in sarcoma initiation and progression." (PMID 31341965, 2019).
T-cell neoplasm (2 papers, 2018 to 2020). "The epigenetic modifier mutations discovered in ANKL suggest similar pathogenetic mechanisms in a subset of ANKL as in related mature T-cell neoplasms harboring similar alterations, such as in SETD2 and TET221,22,46." (PMID 29674644, 2018). "In addition to epigenetic modifiers implicated in all subtypes of T-cell neoplasm (TET2, DNMT3A, KMT2D, KMT2C, SETD2), recurrent mutations of the FAT1 tumor suppressor gene were for the first time recorded in 39% of cases." (PMID 31028364, 2020).
thymoma (2 papers, 2022 to 2024). A neoplasm arising from the epithelial cells of the thymus. "In a recent study, nine out of thirty nine mutated genes (23%) were involved in epigenetic regulation, with 34% of TCs exhibiting recurrent mutations in seven of them (BAP1, ASXL1, SETD2, SMARCA4, DNMT3A, TET2, and WT1), an observation which was not present for thymomas." (PMID 38338833, 2024).
thyroid cancer (2 papers, 2020 to 2024). "We suspected that loss of SETD2 function might also be relevant in the de-differentiation of thyroid cancer." (PMID 32674319, 2020). "Our data also suggest that SETD2 contributes to the de-differentiation of thyroid cancer cells, as reflected by the downregulated expression of four stemness proteins observed after wild-type SETD2 expression was restored in SETD2mut cells." (PMID 32674319, 2020). "In light of the results that emerged from our study, SETD2 appears to be a novel and potentially druggable target for the management of thyroid cancers, in particular those with poor prognoses." (PMID 32674319, 2020). "To minimize the stromal contamination, we isolated a new DNA sample from a macrodissected fragment of TISS-P1.M and subjected it to NGS analysis at higher coverage (1433x) using a smaller custom panel that included SETD2 as well as all the well-known thyroid-cancer-related genes." (PMID 32674319, 2020). "However, no data are available on the frequency of SETD2 mutations in thyroid cancer metastases, where the two SETD2 loss-of-function mutations described in this report were found." (PMID 32674319, 2020).
triple-negative breast carcinoma (2 papers, 2020 to 2025). An invasive breast carcinoma which is negative for expression of estrogen receptor (ER), progesterone receptor (PR), and human epidermal growth factor receptor 2 (HER2). "Such correlation also exists in the triple-negative breast cancer, and the difference is more obvious, indicating that SETD2 mutation is linked to poor prognosis." (PMID 32231741, 2020).
anaplastic thyroid carcinomas (1 paper, 2021). "In fact, histone methyltransferase genes (KMT2A, KMT2C, KMT2D, and SETD2) are increasingly impaired in poorly differentiated and anaplastic thyroid carcinomas." (PMID 33543394, 2021).
Angelman syndrome (1 paper, 2023). A neurogenetic disorder characterized by severe intellectual deficit and distinct facial dysmorphic features. "D’Gama has reported a case (AN00090) harboring a germline missense mutations in SETD2 predicted to be deleterious (responsible for ASD) and a 15q deletion consistent with her diagnosis of Angelman syndrome." (PMID 37025455, 2023).
asthma (1 paper, 2023). "These four genes, SMARCC1, SETD2, KMT2B, and CHD8, were used to construct a nomogram model for predicting the prognosis of patients with severe asthma." (PMID 37245015, 2023). "The nomogram constructed using the four CRs, SMARCC1, SETD2, KMT2B, and CHD8, may be a useful tool for predicting the prognosis of patients with severe asthma." (PMID 37245015, 2023).
autoimmune disease (1 paper, 2025). A disorder resulting from loss of function or tissue destruction of an organ or multiple organs, arising from humoral or cellular immune responses of the individual to their own tissue constituents. "By influencing the biological processes of immune cells, SETD2 participates in the pathogenesis of immune-related diseases, including infection, cancers, autoimmune diseases, and inflammatory diseases." (PMID 40746737, 2025).
brain cancer (1 paper, 2016). A primary or metastatic malignant neoplasm affecting the brain. "Furthermore, we found the mutational status of the histone methyltransferase SET-domain containing-2 (SETD-2) as a significant contributor in kidney, smoking in bladder and lung, and isocitrate dehydrogenase 1 (IDH1) mutational status in brain cancers." (PMID 27966532, 2016).
brain stem glioma (1 paper, 2023). A neuroglial tumor that arises from the brain stem. "A patient with a SETD2 LOF variant developed multiple brain stem gliomas (SETD2-LLS-P2) from age 6 years and a patient (SETD2-R1740W-P4) with Type 1 (R1740W) variant with a metastatic high-grade chondroblastic osteosarcoma in her right proximal tibia and right mandible age 15 years." (PMID 37166351, 2023).
cardiac tumors (1 paper, 2024). "Mutations were found in Arid1a, Setd2, Nf1 and Egfr in all cardiac tumors and in Pdgfra for eight of the tumors." (PMID 38232086, 2024).
Cerebellar hypoplasia (1 paper, 2022). Cerebellar hypoplasia is a descriptive term implying a cerebellum with a reduced volume, but a normal shape and is stable over time. "Recently, a large exome sequencing study of children and adults with DWM and cerebellar hypoplasia expanded the list of genes associated with DWM to include TUBA1A, BRAF, SETD2, FOXP1, PUS3, ARMC9, and PIBF1." (PMID 35202430, 2022).
Cirrhosis (1 paper, 2014). A chronic disorder of the liver in which liver tissue becomes scarred and is partially replaced by regenerative nodules and fibrotic tissue resulting in loss of liver function. "In addition, KIF5C, MYH8, SETD2 and UNC13C mutations were only found in HCC patients in the absence of cirrhosis (0% vs. 11%, p = 0.036 for all four genes)." (PMID 24988079, 2014).
clear-cell carcinoma (1 paper, 2021). "Loss of 3p in clear-cell carcinoma targets driver genes of VHL, PBRM1, SETD2 and BAP1 with collateral deletion of a series passenger genes, amongst which certain genes harbor indispensable functions to maintain cancer cell viability." (PMID 34593007, 2021).
colorectal tumours (1 paper, 2023). "In this study, we found that the simultaneous deletion of SETD2 and SMAD4 in mice led to an increased number and size of colorectal tumours and reduced survival rates, aligning with clinical data." (PMID 37962020, 2023).
craniopharyngioma (1 paper, 2019). A benign, partly cystic, epithelial tumor of the sellar region, presumably derived from Rathke pouch epithelium. "Despite the relatively low mutational burden seen in craniopharyngiomas, we found several unique mutations, including one in the melanocyte-inducing transcription factor (MITF) gene (E318K) and another in the SET Domain Containing 2 gene (SETD2) (R1407 frameshift)." (PMID 31712784, 2019).
cutaneous melanoma (1 paper, 2024). A primary melanoma arising from atypical melanocytes in the skin. "In order to further verify the biomarker value of SETD2 mutation in immunotherapy in cutaneous melanoma, we analyzed the data from Memorial Sloan Kettering Cancer Center (MSKCC), in which samples had undergone immunotherapy." (PMID 38843391, 2024). "In this study, we explored the role of SETD2 in cutaneous melanoma and verified the potential value of it in predicting survival outcome and treatment responses." (PMID 38843391, 2024). "Basing on RNAseq data from skin melanoma (SKCM) samples from TCGA and GTEx (PANCAN, N=19131, G=60499) public database, we evaluated the SETD2 expression levels within cutaneous melanoma samples." (PMID 38843391, 2024).
embryonic carcinoma (1 paper, 2016). "To determine if DNA hypermethylation is a common phenotype induced by SETD2 loss-of-function outside the context of an RCC background, we acutely depleted SETD2 in NCCIT embryonic carcinoma cells using siRNA as we have done previously." (PMID 26646321, 2016).
eosinophilic disorders (1 paper, 2025).
fibrosis (1 paper, 2023). the formation of excess fibrous connective tissue in an organ or tissue in a reparative or reactive process. "Considering that fibrosis is usually the result of chronic inflammation, we also analysed biopsy data from patients with nephritis and patients with renal fibrosis, and the data showed that SETD2 expression is also decreased in patients with renal fibrosis compared to patients with inflammation." (PMID 37933774, 2023).
hypothalamic hamartoma (1 paper, 2023). "In addition, a further patient (SETD2-R1740W-P2) was previously reported to have had a hypothalamic hamartoma." (PMID 37166351, 2023).
leukopenia (1 paper, 2019). "Our analysis of conditional deletion mouse models reveals that leukopenia in Setd2 knockout mice is caused by differentiation arrest at the DN3 or pro-B stage, suggesting an intrinsic requirement for Setd2 in committed lymphopoiesis." (PMID 31350389, 2019).
liver cirrhosis (1 paper, 2025). "An analysis of the clinical liver cirrhosis database revealed that the mRNA expression of Men1 and Setd2 in cirrhotic livers was significantly lower than that in normal livers, whereas the expression of Kmt2a was slightly greater." (PMID 40651612, 2025).
liver fibrosis (1 paper, 2025). "In summary, the present study uncovered the pathological significance of menin/SETD2-mediated H3K36me3 reprogramming in liver fibrosis, providing new insights into the reversible intervention of liver fibrosis." (PMID 40651612, 2025). "Our results provide an interesting proof-of-concept for the therapeutic targeting of H3K36me3 remodeling to inhibit the progression of liver fibrosis promoted by abnormal menin/SETD2 inactivation." (PMID 40651612, 2025). "JIB-04, an H3K36me3 agonist, effectively suppressed KC activation induced by Men1 or Setd2 deletion by reactivating IL-10 expression and further alleviated CCL4-induced liver fibrosis symptoms." (PMID 40651612, 2025).
lung diseases (1 paper, 2023). "Air pollution has been linked to several lung diseases, and particulate matter of 10 μm in diameter (PM10) induces aneuploidy and leads to the generation of chromosomal instability in A549 cells by downregulating SETD2." (PMID 37245015, 2023).
lymph node metastasis (1 paper, 2024). "tested samples of MPLC with lymph node metastasis (LNM) and found that the genes with the highest mutation frequencies in this pair were MUC16, FLNA, MUC4, FAT3, SETD2, and CALR, which implied that MPLC with LNM may have a unique mutation spectrum." (PMID 39411141, 2024).
lymphopenia (1 paper, 2019). Reduction in the number of lymphocytes. "To explore the cause of the lymphopenia phenotype in Mx1-Cre+;Setd2f/f mice and to determine which step of lymphocyte differentiation was affected by Setd2 knockout, we further performed FACS analysis of HSCs and committed progenitors." (PMID 31350389, 2019). "Collectively, these data suggest that Setd2 ablation results in T cell lymphopenia due to blockage of lymphocyte differentiation at the DN3 stage." (PMID 31350389, 2019).
male infertility (1 paper, 2019). The inability of the male to effect fertilization of an ovum after a specified period of unprotected intercourse. "The predominant histone methyltransferase SETD2 (SET domain–containing 2) catalyzes the H3K36me3, and knocking out Setd2 in mouse germ cells causes aberrant spermiogenesis, resulting in complete male infertility." (PMID 31649732, 2019).
malignant mesothelioma (1 paper, 2020). A malignant neoplasm of the pleura or peritoneum, arising from mesothelial cells. "Genome-wide sequencing analyses of malignant mesotheliomas have revealed frequently observed genomic aberrations such as loss of function mutation and/or copy number alterations/deletion of BAP1, SETD2, CDKN2A, and NF2." (PMID 32545767, 2020). "Indeed, our most important finding is the lack of alterations involving BAP1, SETD2, NF2, CDKN2A, PBRM1, and SMARCC1 genes consistently mutated or deleted in malignant mesotheliomas." (PMID 32545767, 2020). "The WDPMs lacked the alterations involving BAP1, SETD2, NF2, CDKN2A/B, LASTS1/2, PBRM1, and SMARCC1 that are frequently found in malignant mesotheliomas." (PMID 32545767, 2020).
metastatic cancer (1 paper, 2016). A carcinoma which has spread from the original site of growth to another anatomic site. "PPP2R1A (E370X), SETD2 (I1608V), SMAD4 (G382T), and AR splicing site mutations were specific to liver metastatic cancer." (PMID 27023146, 2016).
mucosal melanoma (1 paper, 2022). A melanoma that arises from a mucosal site. "SETD2 or H3 lysine 36 histone methyltransferase is mutated in different human cancers, including mucosal melanoma." (PMID 35334544, 2022). "By comparison with cutaneous melanoma, mucosal melanoma has a decreased frequency of BRAF mutations (<10%) and an increased frequency of mutations of CD117 or c-KIT (40%), along with other somatic mutation (SF3B1, ATRX, ARID2, and SETD2)." (PMID 35334544, 2022).
Neurodevelopmental delay (1 paper, 2023). "Pathogenic variants in SETD1A have been reported in association with early onset epilepsy, neurodevelopmental delay and an increased risk of schizophrenia (MIM:618832; MIM:619056), and variants in SETD1B (MIM:619000), SETD2 and SETD5 (MIM:616761) have also been associated with NDDs." (PMID 37166351, 2023).
neuroendocrine neoplasm (1 paper, 2022). Endocrine tumors, also referred to as neuroendocrine tumors (NETs), are defined by a common phenotype which is characterized by the expression of general markers (neuron specific enolase, chromogranin, synaptophysin) and hormone secretion products. "However, mutations in various genes related to TKs were detected in the tumor samples (JAK3, NRAS, NTRK2, NF1, SETD2) suggesting frequent alteration of TK pathways for neuroendocrine neoplasms." (PMID 36743926, 2022).
oral cancer (1 paper, 2025). "However, SETD2 (histone lysine methyltransferase SETdomain containing 2) mutations has been implicated in different cancers, but studies showing its occurrence in oral cancer are scarce." (PMID 40457841, 2025).
osteoporosis (1 paper, 2018). A condition of reduced bone mass, with decreased cortical thickness and a decrease in the number and size of the trabeculae of cancellous bone (but normal chemical composition), resulting in increased fracture incidence. "And the SETD2-deficient mice might serve as a novel model to investigate age-related osteoporosis." (PMID 30422989, 2018). "Overall, our study identified mammalian SETD2 as a novel regulator of MSC fate and suggested that modulation of H3K36me3 could have a therapeutic potential in osteoporosis." (PMID 30422989, 2018).
otitis (1 paper, 2023). "In addition, some of the patients with SETD2 mutations would present defects of multiple systems and recurrent otitis." (PMID 37025455, 2023).
ovarian tumors (1 paper, 2023). "Responses were observed in ovarian tumors with LOF alterations in gBRCA1 (n = 2), gRAD51C (n = 2) and SETD2 (n = 1)." (PMID 37277454, 2023).
Pancreatic NETs (1 paper, 2025). "Pancreatic NETs frequently exhibit changes in genes such as MEN1, DAXX, ATRX, TSC1, TSC2, CDKN1A, and CDKN1B, along with alterations in CDKN2A and SETD2 in metastatic lesions." (PMID 41426335, 2025).
periodontitis (1 paper, 2019). An acute or chronic inflammatory process that affects the tissues that surround and support the teeth. "Meanwhile, the different role of hnRNPL and SET domain containing 2 (Setd2) may provide some implication of the treatment of periodontitis patients simultaneously suffering from osteoporosis." (PMID 30746871, 2019).